ENSG00000239080
Synonyms: LOC124905271
Gene: Small nucleolar RNA gene on chromosome X (136,134,317 to 136,134,420, reverse strand). Ensembl gene ENSG00000239080.
Gene Ontology:
Biological process: RNA processing
Cellular component: nucleolus
Homologues: Paralogues in human: SNORD13 (88% identical), SNORD13D (86% identical), SNORD13E (86% identical), SNORD13P3 (86% identical), SNORD13P1 (83% identical).